MFN2 (mitofusin 2)
Diseases named in the same sentence as MFN2 in open-access papers (continued):
Sharing a sentence is not in itself a finding about the gene and the disease.
glioma (4 papers, 2020 to 2024). A benign or malignant brain and spinal cord tumor that arises from glial cells (astrocytes, oligodendrocytes, ependymal cells). "YME1L silencing or KO resulted in reduction of TIMM44-dependent mitochondrial genes, including Opa1, Mfn1 and Mfn2, in P1 glioma cells." (PMID 36438483, 2022). "Of note, MFN2 siRNA reduced MFN2 expression by about 75% in A172 glioma cells." (PMID 33086741, 2020). "In glioma cell cytoplasm, overexpression of MIF suppressed DRP1 and p-DRP1 expression while enhancing OPA1 and MFN2 expression." (PMID 38405130, 2024). "MRE11, RTCB, TIMM9 and METTL14 were up‐regulated in gliomas, while CDPIT and MFN2 were down‐regulated." (PMID 35044082, 2022). "Opa1, Mfn1 and Mfn2, TIMM44-dependent mitochondrial genes, were increased in TIMM44-overexpressed P1 glioma cells." (PMID 36438483, 2022). "Furthermore, overexpression of METTL3 up-regulated DRP1 and p-DRP1 proteins in both glioma cell cytoplasm and mitochondria while down-regulating OPA1 and MFN2 proteins." (PMID 38405130, 2024). "This study confirmed that LINC00475-S could promote mitochondrial fission in glioma cells by increasing DRP1 and p-DRP1 levels while down-regulating OPA1 and MFN2 expression." (PMID 38405130, 2024). "In the mitochondria of glioma cells, MIF overexpression markedly inhibited DRP1 and p-DRP1 expression while increasing OPA1 levels, with no substantial impact on MFN2 expression." (PMID 38405130, 2024).
optic neuropathies (4 papers, 2022 to 2024). "The MFN2 p.Arg259Cys variant was found in a CMT2 proband who developed optic neuropathy in adulthood." (PMID 37712079, 2023). "Mutations in genes encoding other mitochondrial quality control proteins, including mitofusin 2, DRP1 and paraplegin, cause syndromic optic neuropathy, further connecting mitochondrial function to retinal degeneration." (PMID 38324746, 2024).
ovarian failure (4 papers, 2015 to 2024). "Our findings regarding accelerated follicular depletion in Mfn2-/- mice are supported by a previous study showing decreased MFN2 expression in mice that develop apoptotic oocyte loss and ovarian failure in response to cisplatin treatment." (PMID 31204316, 2019). "Similarly, targeted MFn2 deletion has been earlier documented as a critical contributor to impaired oocyte granulosa cell development that results in ovarian failure or deficiency." (PMID 38561673, 2024). "Therefore, it is important to further investigate the participation of mitofusin-2 in mitochondrial ovarian dysfunction associated with PCOS." (PMID 38561673, 2024). "MFN2 knockout mice drastically decreased in primordial and growing follicles at 12 months of life, leading to ovarian failure." (PMID 37892483, 2023).
polyneuropathy (4 papers, 2011 to 2019). A disease or disorder affecting more than one nerve. "Charcot–Marie tooth disease is a hereditary polyneuropathy caused by mutations in Mitofusin-2 (MFN2), a GTPase in the outer mitochondrial membrane involved in the regulation of mitochondrial fusion and bioenergetics." (PMID 31640251, 2019). "The MFN2 c.475-1G>T, which is carried by Patient 10, was found to cause a deletion of 4 amino acids (p.T159_Q162del), and this may explain his relatively mild polyneuropathy." (PMID 22206013, 2011). "Genetic testing was performed according to polyneuropathy type; demyelinating/mixed: PMP22 duplication, MPZ, EGR2, LITAF, NEFL, PMP22, GJB1, axonal: MFN2, MPZ, NEFL, and GJB1." (PMID 24053775, 2013).
renal fibrosis (4 papers, 2022 to 2025). A final common manifestation of a wide variety of chronic kidney diseases characterized by glomerulosclerosis and tubulointerstitial fibrosis. "Furthermore, Cui and colleagues found that the Mitofusin 2 (MFN2) downregulation in macrophages enhances ROS and inhibits mitophagy, driving renal fibrosis." (PMID 40497970, 2025). "Another study found that downregulation of mitofusin 2 (MFN2) led to macrophage recruitment to the kidney and polarization towards the pro-fibrotic M2 phenotype by enhancing OS and inhibiting macrophage mitophagy, thereby promoting collagen deposition and renal fibrosis." (PMID 39183973, 2024).
Sensorimotor neuropathy (4 papers, 2020 to 2025). "Heterozygous MFN2 mutations most commonly cause inherited sensorimotor neuropathy (Chung 2006, Verhoeven 2006, Neusch 2007)." (PMID 40759924, 2025). "Charcot–Marie‐Tooth type 2A (CMT2A) is an inherited sensorimotor neuropathy associated with mutations within the Mitofusin 2 (MFN2) gene." (PMID 38722298, 2024). "A recent study of dermal fibroblasts from patients with sensorimotor neuropathy due to heterozygous MFN2 loss-of-function mutations also found no overt mitochondrial network abnormalities nor mitochondrial dysfunction in similar conditions." (PMID 40759924, 2025). "Primary anatomical and/or functional defects in humans with MFN2 R707W homozygosity have been observed only in adipose tissue and peripheral nerves, with some but not all people reported to have sensorimotor neuropathy." (PMID 36722855, 2023).
acute kidney injury (3 papers, 2025). Sudden and sustained deterioration of the kidney function characterized by decreased glomerular filtration rate, increased serum creatinine or oliguria. "Furthermore, SIRT3 mediates the ubiquitination and degradation of mitofusin 2, which inhibits ischemia-reperfusion-induced acute kidney injury." (PMID 40771930, 2025). "LRRK2, a kinase involved in mitochondrial homeostasis, and has been shown to exacerbate acute kidney injury (AKI), by degrading Mitofusin-2 (MFN2) leading to mitochondrial fragmentation and impaired bioenergetics." (PMID 41567979, 2025).
cervical carcinoma (3 papers, 2019 to 2023). A carcinoma arising from either the exocervical squamous epithelium or the endocervical glandular epithelium. "Other reports have indicated that high expression of MFN2 is linked to poor prognosis in cervical cancer, contradictory to our findings." (PMID 36877954, 2023). "In order to verify the effect of Mfn2 protein against the cervix carcinoma in vivo, we examined the therapeutic effect of Adv-mfn2 on xenografted cervix carcinoma in a mouse tumor model for a 2-week treatment." (PMID 31384172, 2019). "The nucleus of cervix carcinoma cells treated with Adv-mfn2 was pycnosis and fragmented into several parts in the analyzed histological section." (PMID 31384172, 2019). "This study aimed to investigate the effect of Mfn2 on cell proliferation, and cell-cycle in Hela cervical carcinoma cell lines." (PMID 31384172, 2019). "During the treatment, the volume of xenografted cervix carcinomas treated with Adv-mfn2 increased slowly, whereas the volume of the tumors treated with Adv-control increased faster than the Adv-mfn2 group." (PMID 31384172, 2019). "The xenografted cervical carcinoma mouse model was examined to confirm the effect of Mfn2 in Hela cells in vivo." (PMID 31384172, 2019). "Then, the xenografted cervix carcinoma mouse model was used to confirm the effect of Mfn2 in Hela cells in vivo and the expression of Ras-NF-κB signaling pathway in vivo." (PMID 31384172, 2019). "In our early studies, we found that PTD4-apoptin fusion protein could upgrade Mfn2 expression in cervical carcinoma cells." (PMID 31384172, 2019). "Based on our research, we propose that Mfn2 may be a novel target to the therapy of cervical carcinoma in the future." (PMID 31384172, 2019). "To detect whether the adenovirus took the mfn2 gene into the cervix carcinoma cells, we uesd the qRT-PCR to obverse the expression of mfn2 gene in Hela cells." (PMID 31384172, 2019).
clear cell renal cell carcinoma (3 papers, 2023 to 2025). "In conclusion, MFN2 can be used as a novel prognostic marker for renal clear cell carcinoma and requires further investigation of its role in tumor development." (PMID 37845657, 2023). "We have verified in vitro cell experiments to correlate the lower level of MFN2 expression with the ability of renal clear cell carcinoma cells to proliferate and migrate.However, our study still has some limitations." (PMID 37845657, 2023). "In this study, we analyzed the expression of MFN2 in renal clear cell carcinoma tissues and normal kidney tissues through the Cancer Genome Atlas (TCGA) database and our clinical samples.Enrichment analysis was performed to determine MFN2-related pathways and biological functions." (PMID 37845657, 2023). "Moreover, high‐glucose/high‐fat‐treated cardiomyocyte mitochondria became fragmented and the expression of MFN2 was significantly reduced, whereas this protein was shown to suppress the accumulation of LDs and the progression of clear cell renal cell carcinoma." (PMID 40418213, 2025). "Taken together, MFN2 could be a new molecular candidate to treat renal clear cell carcinoma." (PMID 37845657, 2023). "Firstly, we only verified the expression of MFN2 and its correlation with prognosis through the TCGA database, which may have some bias; secondly, we need to further elucidate how MFN2 plays a role in renal clear cell carcinoma through in vivo experiments and in vitro mechanistic experiments." (PMID 37845657, 2023). "Mitofusin 2 (MFN2) plays an important role in many tumors, but how its role in renal clear cell carcinoma needs further research." (PMID 37845657, 2023).
cognitive decline (3 papers, 2017 to 2023). "On the other hand, the forced overexpression of MFN2 in P301S human tau transgenic mice suppressed tau pathology-induced neurodegeneration and cognitive decline." (PMID 37623221, 2023). "MFN2 deletion induces age-dependent depletion, neurogenesis defects and cognitive decline through impaired mitochondrial dynamics, might be upstream of neural stem cell (NSC) self-renewal." (PMID 35370565, 2022). "The p.Arg274Trp MFN2 mutation detected by us is not causative for mental retardation alone, in contrast to the p.Arg104Trp mutation that results in sensorineural hearing impairment, peripheral neuropathy and mild cognitive decline." (PMID 28076385, 2017).
colitis (3 papers, 2022 to 2024). Inflammation of the colon. "MFN2 expression was reduced in colitis, and ARRB1 deficiency exacerbated this decrease." (PMID 39246845, 2024). "MFN1, MFN2, OPA1, and p-DRP1 levels increased in a model of DSS-induced colitis." (PMID 35035669, 2022).
coronary artery diseases (3 papers, 2023). "We finally identified ATG5, TOMM20, MFN2 transcriptionally differed between MI and stable coronary artery diseases." (PMID 37304955, 2023).
distal myopathy (3 papers, 2025 to 2026). Distal myopathy refers to a group of muscle diseases which share the clinical pattern of predominant weakness and atrophy beginning in the feet and/or hands. "Here, our characterization of cells from a patient exhibiting distal myopathy who carried the candidate pathogenic MFN2 Q367H variant provides novel mechanistic insight into MFN2-mediated pathology." (PMID 40175090, 2025). "The present study describes a novel pathogenic variant in MFN2 from a patient with late-onset distal myopathy and links pathogenic perturbation of MFN2 function to mitochondrial DNA release and inflammation." (PMID 40175090, 2025). "Here, we report a novel MFN2 variant, Q367H, in a patient diagnosed with late-onset distal myopathy." (PMID 40175090, 2025). "Mitochondrial DNA (mtDNA)-mediated inflammation has recently emerged as an additional pathogenic mechanism potentially involved in CMT2A, following the identification of the novel MFN2 Q367H variant in a patient with late-onset distal myopathy." (PMID 41237781, 2025). "Here, we identified an uncharacterized MFN2 variant, Q367H, in a patient diagnosed with late-onset distal myopathy, but without peripheral neuropathy." (PMID 40175090, 2025).
endotoxemia (3 papers, 2021 to 2022). "The enhanced expression of Drp1 and suppressed expression of Mfn2 caused by endotoxemia and MV at VT = 10 mL/kg were substantially reversed in HIF-1α-deficient mice." (PMID 35163007, 2022). "One of our ongoing investigations is aimed at determining the potential signaling pathway between Beclin‐1 and Mfn2 in cardiac MAMs and the responses of these signaling components to endotoxemia." (PMID 33733054, 2021). "To investigate whether sulfenylation of Mfn2 also occurs during inflammation in vivo, we used the experimental model of endotoxemia which induces profound inflammatory injury." (PMID 33980844, 2021).
frontotemporal dementia (3 papers, 2023 to 2026). Frontotemporal dementia (FTD) comprises a group of neurodegenerative disorders, characterized by progressive changes in behavior, executive dysfunction and language impairment, as a result of degeneration of the medial prefrontal and frontoinsular cortices. "By analyzing a virtual panel of genes associated with motor neuron disease, frontotemporal dementia and hereditary neuropathies, the affected probands were found to carry the heterozygous variant in the MFN2 gene (reference sequence NM_014874.4) c.581A>C p (Asp194Ala)." (PMID 37547466, 2023). "More recently, in a mouse model of ALS, MFN2 protein has been found to interact in complex with Transactive response DNA-binding protein of 43 kDA (TDP-43), involved in frontotemporal lobar degeneration (FTLD) and ALS." (PMID 37547466, 2023).
glioblastoma (3 papers, 2020 to 2026). The most malignant astrocytic tumor (WHO grade IV). "Furthermore, UALCAN analysis showed that Mfn2 was lower in glioblastoma multiforme, sarcoma, and thymoma, and the higher level of Mfn2 was correlated with poorer OS in patients with sarcoma and thymoma." (PMID 41531728, 2026). "Inhibition of BCAA metabolism promotes glioblastoma cell apoptosis by disrupting mitochondrial dynamics mediated by mitofusin 2 (Mfn2) and inhibiting the PI3K/AKT/mTOR pathway, making it a potential novel therapeutic target for treating glioblastoma." (PMID 40438606, 2025). "The long-term effect of increasing MFN2 expression on tumor transformative potential, absent of a concurrent apoptosis-inducing treatment, was not studied in this present work, but remains an interesting prospect for glioblastoma therapy." (PMID 33162811, 2020).
hearing loss (3 papers, 2021 to 2023). "In accord with this, recent data showed that patients with the Mfn2 variant (D414V) exhibit a hearing loss phenotype." (PMID 37395319, 2023).
Infertility (3 papers, 2021 to 2024). "In a previous study, severe developmental delays and embryonic deaths caused by placental defects were observed in Mfn2 knockout mice, and infertility occurred in female mice after oocyte-specific knockout of Mfn2." (PMID 34094652, 2021). "The present observations are similar to earlier studies, which attributed an aberrant follicular maturation and subsequent infertility to decreased expression of MFn2." (PMID 38561673, 2024).
injury (3 papers, 2024 to 2025). Damage inflicted on the body as the direct or indirect result of an external force, with or without disruption of structural continuity. "However, preconditioning with mitoquinone mesylate to prevent the decline of MFN2 expression or directly overexpressing MFN2 was shown to improve ER function and mitigate arsenic-induced acute lung injury (Li MD." (PMID 40177356, 2025). "In I/R-induced liver injury, ALR not only enhanced the mitochondrial translocation of PINK1 and Parkin but also induced MFN2 expression." (PMID 38812059, 2024).
lipid metabolism disorder (3 papers, 2022 to 2025). "The improvement of lipid metabolism disorder may occur through increasing liver mitochondrial biosynthesis-related genes (PGC-1α and TFAM) and restoring mitochondrial dynamics-related gene (MFN2 and DRP1) mRNA levels." (PMID 36676939, 2022).
multiple lipomatosis (3 papers, 2021 to 2025). "The presence of lipomas is common, particularly in cases associated with variants of LMNA, MFN2, or LIPE." (PMID 40452043, 2025).
neuroblastoma (3 papers, 2019 to 2022). Neuroblastoma (NB) is the most common solid, extracranial childhood tumor. "Overexpressing Mfn2 increased ATP production and activated Sirt3 in mouse neuroblastoma N2a cells." (PMID 35386849, 2022).
preeclampsia (3 papers, 2016 to 2024). Preeclampsia is a hypertensive disorder of pregnancy that is characterized by new-onset hypertension with proteinuria presenting after 20 weeks of gestation, and depending on mild or severe forms may initially present with severe headache, visual disturbances, and hyperreflexia. "Similar to HIF-1α, Mfn-2 also shows an increase secondary to placental hypoxia, playing a role in the pathophysiology of preeclampsia as a key transcription factor regulating cellular responses to hypoxia and low oxygen tension." (PMID 39166673, 2024). "Our study provides a new perspective on the role of Mfn-2 as a novel biomarker for maternal and fetal/neonatal complications in women with suspected or confirmed preeclampsia." (PMID 39166673, 2024). "The aim of this study was to evaluate mitofusin-2 levels and fetal Doppler ultrasonography effects in patients with severe preeclampsia." (PMID 39166673, 2024). "The mitochondrial fusion proteins mitofusin 1, MFN2, and optic atrophy 1 are downregulated in the placentas of women with preeclampsia." (PMID 38390447, 2024). "In conclusion, we found that serum Mfn-2 concentrations, an important mitochondrial biomarker, are significantly elevated in women with pregnancy complicated by preeclampsia compared to healthy controls, with this elevation being more pronounced in severe preeclampsia." (PMID 39166673, 2024). "However, maternal serum MFN2 levels were higher in patients with preeclampsia." (PMID 38390447, 2024). "Therefore, other factors limiting our study include not evaluating the serum Mfn-2 concentrations before the onset of preeclampsia and not monitoring changes in serum concentrations until delivery." (PMID 39166673, 2024).
premature ovarian failure (3 papers, 2015 to 2020). "Knockdown of mitochondrial fusion gene Mfn2 by siRNA in immature oocytes results in a decline in oocyte maturation and fertilization and lower expression of Mfn2 is found in cisplatin-induced premature ovarian failure in mice." (PMID 31204316, 2019).
prostate carcinoma (3 papers, 2017 to 2023). A carcinoma that arises from epithelial cells of the prostate gland. "Another prostate cancer-specific target of miR-93, MFN2, was shown to suppress breast and thyroid cancer progression through AKT signaling." (PMID 36688696, 2023). "In the present study, we have clearly revealed that FABP5 activated expression of metabolic genes (ATP5B, LCHAD, ACO2, FH and MFN2) via a novel signaling pathway in an ERRα (estrogen-related receptor α)-dependent manner in prostate cancer cell lines." (PMID 30167092, 2018).
retinal degeneration (3 papers, 2014 to 2024). Degeneration of the retina. "When the Mfn1/Mfn2 ratio and the mitochondrial fusion/fission are imbalanced, it will induce retinal degeneration using mitophagy." (PMID 38001811, 2023). "Therefore, our study suggests that manipulation of mitochondrial fusion component Mfn2 could be a potentially promising therapeutic strategy to forestall retinal aging and aged-associated retinal degeneration; yet further investigations are required to explore the practical approach." (PMID 24987494, 2014).
sarcoma (3 papers, 2020 to 2026). A usually aggressive malignant neoplasm of the soft tissue or bone. "The significant association between high Mfn2 expression and poorer OS in patients with sarcoma and thymoma suggests that inhibition of mitochondrial fusion may represent a potential therapeutic strategy." (PMID 41531728, 2026).